CCL2 (C-C motif chemokine ligand 2)
Diseases named in the same sentence as CCL2 in open-access papers (continued):
Sharing a sentence is not in itself a finding about the gene and the disease.
liver fibrosis (continued). "To investigate the role of Ccl2 and Ccl8 in pMDMs intrahepatic infiltration and liver fibrosis progression, we treated mice with Bindarit, a dual inhibitor of Ccl2 and Ccl8, during the construction of liver fibrosis model in Tet2ΔMye mice." (PMID 41474968, 2026). "Irradiation at high radiation doses (>30 Gy) results in the development of liver fibrosis, whereas lower doses affect hepatic function by inducing inflammatory and oxidative stresses, in which the expression of cytokines, such as IL-6 and CCL2, increases with the activation of the NFκb signaling." (PMID 40141336, 2025). "Additionally, the expression of genes involved in lipids synthesis, such as ATGL, SCD1, and liver fibrosis, such as CCL2 decreased with co‐administration." (PMID 40231957, 2025). "For instance, miR-155 depletion inhibits monocyte infiltration by suppressing CCL2 expression, and KCs exhibit a predominance of the M2 phenotype due to increased CCAAT enhancer-binding proteinβ (C/EBPβ) expression during liver fibrosis associated with NASH and ASH." (PMID 41479922, 2025). "Notably, a dual inhibitor of CCR2/CCR5, known as Cenicriviroc (CVC), effectively blocks CCL2-mediated monocyte recruitment to the liver and exhibits anti-fibrotic effects in a mouse model of liver fibrosis." (PMID 40977736, 2025). "They show that CCL2, IL-18, and IL-33 are involved in distinct stages of the disease and, particularly, in the onset of the disease, as well as in the hepatic fibrosis that may occur during the chronicity." (PMID 40565198, 2025). "Furthermore, in liver fibrosis models, CCL2 and other pro-inflammatory markers are elevated alongside COL1A1 overexpression, indicating a synergistic role in fibrosis." (PMID 40606673, 2025). "During liver fibrosis, the levels of endotoxins, such as lipopolysaccharide (LPS) increase in the liver, activating the Kupffer cells, the liver-resident macrophages that produce various inflammatory cytokines and chemokines (e.g., CCL2)." (PMID 41196648, 2025). "Additionally, HBeAg can promote HSC proliferation, movement, and contraction in a macrophage-dependent manner, inducing CCL2 production that activates HSCs and worsens liver fibrosis." (PMID 39850880, 2024). "Moreover, recent developments in nanotechnology have shown promise in the treatment of liver fibrosis through the modulation of CCL2 levels." (PMID 39850880, 2024). "However, during pathological conditions such as hepatic steatosis, liver inflammation, and liver fibrosis, a large number of peripheral monocyte-derived LAMs precursor cells are recruited to the liver by the CCL2/CCR2 axis and then differentiate into LAMs." (PMID 39635524, 2024). "Herein, we found the expression of CCL2 increased with liver fibrosis degree." (PMID 36183106, 2022). "Activated KC generates various types of mediators of liver fibrosis progression (e.g., TGF-β, PDGF, IL-1β, MMPs, CCL2, cysteine-3, etc.)and also accelerates the progression of liver fibrosis by activating HSC to produce large amounts of collagen, allowing ECM to settle and aggregate." (PMID 35529927, 2022). "Knockout of CCR2 or inhibition of CCL2 could alleviate liver fibrosis, indicating that Ly6Chi monocytes/macrophages are pro-fibrotic cells and play roles in aggravating tissue damage." (PMID 35990625, 2022). "CCL2-dependent infiltrating macrophages promote angiogenesis in progressive liver fibrosis." (PMID 33614685, 2021). "Furthermore, in consistent to what we found in the in vitro study, the expression of CCL2 increased with liver fibrosis progress." (PMID 33614685, 2021). "Yet, so far, only a few studies have explored whether CCL2 independently affects the phenotype and function of monocytes/macrophages in the process of liver fibrosis." (PMID 33614685, 2021). "To explore whether CCL2/CCR2 axis has a crucial role in macrophage phenotypic changes during liver fibrosis, we treated the M0MΦ with recombinant human CCL2 or its specific receptor antagonist INCB-3284." (PMID 33614685, 2021).
liver fibrosis (continued). "In addition, rottlerin treatment also suppressed TGFβ1-induced expression of ACTA2, COL1A1, COL1A2, and CCL2, the expression of which is greatly increased in HSCs of liver fibrosis patients." (PMID 32210801, 2020). "In addition, chemokines also play a part in the fibrotic process of various injury models, for example, theCXCL12-CXCR4 chemokine axis is involved in liver fibrosis, and CCL2 is involved in pulmonary fibrosis in lung injury." (PMID 33071808, 2020). "Therefore, inhibition of monocyte recruitment through depletion of the pro-inflammatory signal CCL2 results in attenuation of liver fibrosis." (PMID 27999564, 2016). "In addition, pharmacological inhibition of CCL2 by the RNA-aptamer mNOX-E36 attenuates liver fibrosis, thereby strengthening a pro-fibrotic function of Ly6Chigh macrophages." (PMID 27999564, 2016). "In addition, we also used immunostaining to evaluate the expression of thrombospondin 1 (Thbs1) and chemokine (C-C motif) ligand 2 (Ccl2), two factors that are known to contribute to inflammation and hepatic fibrosis." (PMID 27226149, 2016). "This is in agreement with the findings that targeting Kupffer cells by GdCl3 ameliorates carbon tetrachloride-induced liver fibrosis, and that pharmacological inhibition of the chemokine CCL2 diminishes liver macrophage infiltration thereby attenuating steatohepatitis during chronic hepatic injury." (PMID 26317423, 2015). "Of interest, chemokine genes, such as CCL5, CCL2 and CXCL10, could activate human hepatic stellate cells, which are associated with hepatic fibrosis, and CXCL10 is an important gene for the treatment response of interferon treatment." (PMID 26133378, 2015). "Our findings reveal that Tet2−/− pMDMs are a major source of elevated Ccl2 and Ccl8 in Tet2ΔMye-CCl4 mice, and Tet2−/− monocytes showed an increased expression of Ccr2 and Ccr3, which, thus, created a positive feedback loop that amplifies MDMs infiltration and liver fibrosis." (PMID 41474968, 2026). "In addition to mechanism exploration, anti-hepatic fibrosis therapeutic strategies targeting macrophages have also been a hot research topic, and the discovery of CC chemokine ligand 2 (CCL2) antagonists and bone marrow-derived macrophages have attracted extensive attention in the field." (PMID 40406489, 2025). "Notably, it inhibited the expression of both CCL2 and CCL7, also known as monocyte chemotactic protein 3 (MCP3), which are upregulated in active HSC and cause a local inflammatory reaction during liver fibrosis." (PMID 41196648, 2025). "In liver fibrosis, enhanced NEDDylation is positively related to increased caspase 3 activity to induce hepatic stellate cell apoptosis, whereas inhibited NEDDylation reduces chemokine (C-X-C motif) ligand 1 and C-C motif chemokine ligand 2 (CCL2) expressions to ameliorate apoptosis." (PMID 39697538, 2024). "We demonstrated increased liver CCL2 (which encodes MCP-1) expression in patients with NASH, and commensurately, a 100-fold increase in hepatocyte Ccl2 expression in a mouse model of NASH, accompanied by increased liver monocyte-derived macrophage (MoMF) infiltrate and liver fibrosis." (PMID 36752206, 2023). "The qPCR results showed that overexpression of miR-552-3p significantly reduced the mRNA levels of fibrotic genes (Col1a1, Col3a1, Timp-2) and inflammatory genes (Il-6, Ccl2, F4/80) in mice livers, which demonstrated that miR-552-3p could reduce liver fibrosis and inflammation in mice again." (PMID 37496991, 2023). "Notably, CCL2 is one of the chemokines involved in liver fibrosis." (PMID 37693903, 2023). "In addition to their role in liver fibrosis, it is argued that high levels of CCL2 can severely affect the course of HIV infection by up-regulating HIV-co-receptor CXCR4 on CD4+ T cells and polarization of helper T cells towards Th2 phenotype, a hallmark of progressive HIV disease." (PMID 25528160, 2014).
liver fibrosis (continued). "Thus, above clinical studies and experimental models clearly suggest CCL2 a key mediator of hepatic fibrosis and their potential blocking may offer improved clinical outcome." (PMID 25528160, 2014). "In our opinion, the fibrosis biomarker properties of CCL-2 and sFasL warrants further investigation and validation as they may augment current clinical practice through their combination with existing non-invasive liver fibrosis tests, for example, APRI." (PMID 23405244, 2013). "Additionally, to enhance the performance of known non-invasive biomarkers of liver fibrosis, there may be a value in combining them with CCL-2 and sFasL in a comprehensive panel." (PMID 23405244, 2013). "Hence, we hypothesized that stem cell-derived CCL2 signalling to recruit Ly6C+ macrophages provides a critical microenvironment for determining the immunosuppressive capacity of MSCs and has a profound effect on the treatment of liver fibrosis." (PMID 40050288, 2025). "MoMFs can be attracted to the liver via the CCL2/CCR2, CCL5/CCR5, and CCL1/CCR8 chemokine axis, thereby aggravating liver fibrosis." (PMID 41479922, 2025). "CCL2, also known as monocyte chemoattractant protein 1 (MCP1), plays a pivotal role in inducing local inflammatory responses during liver fibrosis by facilitating the chemotactic migration of monocytes into damaged liver tissue." (PMID 41196648, 2025). "Cencriviroc, an antagonist of CCL2 and CCL5 receptors (CCR2/CCR5), is reportedly beneficial, with notably improved liver fibrosis in the treated patients." (PMID 40077628, 2025). "Analysis of the liver fibrosis expression dataset GSE84044 from the GEO database identified 10 key genes in the protein interaction network, including CCL2, highlighting its importance in fibrosis and inflammation." (PMID 39850880, 2024). "It has been reported that HSCs promote hepatic macrophage infiltration through the CCL2/CCR2 pathway and induce M2 polarization to aggravate liver fibrosis." (PMID 38545255, 2024). "Recently, it has been reported that Notch-induced Ccl2 expression in hepatocytes is both necessary and sufficient for liver infiltration of MDMs and NASH-induced liver fibrosis." (PMID 39542242, 2024). "In contrast to Foxo1M-KO, Foxo1/Notch1M-DKO augmented liver fibrosis, with concomitant increases in the mRNA expression of profibrotic genes, including αSMA, Col1α1, TGF-β1, CCL2, and TIMP1, in the liver after HFD feeding." (PMID 39122845, 2024). "KCs can also release pro-inflammatory cytokines, including TNF-α and IL-1β, and recruit peripheral mononuclear macrophages to the liver through the CCL2/CCR2 axis, further aggravating liver fibrosis." (PMID 39635524, 2024). "Compared with the WT mice, the Foxo1/YAPM-DKO mice exhibited significantly increased serum ALT levels, liver fibrosis, and mRNA levels of αSMA, Col1α1, TGF-β1, CCL2, and TIMP1 in the HFD-challenged livers." (PMID 39122845, 2024). "Autophagy of LSEC also enables chemokines, inflammatory factors such as C-C chemokine ligand 2 (CCL2), C-C chemokine ligand 2 (CCL5), and interleukin-6 (IL-6) are enhanced, promoting the hepatic inflammatory response and thus liver fibrosis." (PMID 35529927, 2022). "CCR2 (a receptor for CCL2) and CCR5 (a receptor for CCL3 and CCL4) have been proposed to be targets for antifibrotic therapy due to their ability to promote liver fibrosis and macrophage infiltration." (PMID 35662287, 2022). "In the present study, we found that aHSCs aggregate the macrophages through CCL2/CCR2 pathway and induce M2 phenotypic transformation during liver fibrosis." (PMID 33614685, 2021). "In conclusion, we found increased expression of hepatic CD163 and CCL2 in patients with HBV-related fibrosis; the expression increased dramatically with further progression of liver fibrosis." (PMID 33614685, 2021).
liver fibrosis (continued). "The result is an epigenetically-regulated transcriptional program involving secretion of TGF-β1, CTGF, p16, CCL2 and SA-β-gal, ultimately leading to a profibrogenic micro-environment, HSC activation, and enhanced liver fibrosis." (PMID 34805276, 2021). "Based on results of network pharmacology, it was known that flavonoids can possibly suppress liver fibrosis by inhibiting the IL-17 signaling pathway, which includes NF-κB, AP-1, IL-6, IL-1β, TNFα, IFN-γ, CCL2, COX2, MMP1, MMP3, and MMP9." (PMID 33551818, 2020). "The CCL2, also called monocyte chemoattractant protein 1 (MCP1), is a proinflammatory cytokine secreted by HSC and Kupffer cells in the liver, and promotes hepatic fibrosis by stimulating the recruitment of monocytes to the injured liver." (PMID 30679661, 2019). "Taken together, these observations render the CCL2/CCR2 and the CX3CR1 pathways important targets for developing potential therapies for the treatment of liver fibrosis." (PMID 25852818, 2015). "HSCs express a multitude of chemokines, including the CC chemokines CCL2, CCL3, and CCL5, which are involved in cell chemotaxis and liver fibrosis." (PMID 25076488, 2014). "Hence, the inhibition of CCL2/CCR2, CCL5/CCR5, and CCL1/CCR8 chemotaxis shows potential efficacy to repair liver fibrosis." (PMID 39635524, 2024). "Hepatocyte-specific Ccl2 knockout mice showed reduced MDM infiltration and liver fibrosis." (PMID 39542242, 2024). "In an animal model, the levels of IL-17 and CCL2 in the liver and intestinal tissues of mice treated with HF+DSS were higher than those of mice treated with HF or DSS alone, and were also found to be related to liver fibrosis." (PMID 38698841, 2024). "Impressively, Mφtgmif showed even higher levels of CCL2 expression than LPS/IFN‐γ‐Mφ, indicating that Mφtgmif may have higher chemotactic potential, assisting in the reversal of liver fibrosis." (PMID 38247166, 2024). "By 2 weeks after alcohol cessation, Tgfb1, Tnf, and Ccl2 were decreased to the levels of control-fed mice (high-fat diet without alcohol) that do not develop liver fibrosis by Sirius red staining." (PMID 37943941, 2024). "However, ablation of hepatocyte-derived MCP-1 largely suppressed NASH diet–induced increase in liver Ccl2 and partially abrogated HSC activation and liver fibrosis." (PMID 36752206, 2023). "In mice, the deletion or antibody blockade of CCL2 ameliorated NASH progression and liver fibrosis." (PMID 37296834, 2023). "The heat map showed that GXF could significantly inhibit the expression of some chemokine-related genes such as CCL2, CXCL6 and CX3CL1, suggesting that GXF may alleviate CCl4-induced liver fibrosis by inhibiting the recruitment of related immune cells." (PMID 35180857, 2022). "Consistently, the mRNA levels of inflammatory mediators TNF-α and IL-1β, as well as IL-6, ICAM, CCL2, CXCL2, and TGF-β, which were indicated as progressive inflammatory response and liver fibrosis, were significantly elevated in the liver of MFG-E8 knockout mice compared with the MCD-WT group." (PMID 35769208, 2022). "Hepatic macrophages also enhance liver fibrosis through the release of IL-1β, TNF-α, CCL2 and PDGF." (PMID 34805276, 2021). "There is growing evidence that CCR2/CCR5 and its ligands, including MCP-1 (CCL2) and RANTES (CCL5), are involved in the pathogenesis of liver fibrosis through the promotion of monocyte/macrophage mobilization and tissue infiltration, and the activation of HSCs after liver injury." (PMID 34938271, 2021). "These experiments indicate that interventions to reduce NOX4 or to increase CCR2/CCL2 turnover may attenuate ethanol mediated oxidative stress in HSC at early stages, that later on may result in decreased liver fibrosis." (PMID 28383062, 2017).
liver fibrosis (continued). "Inhibition of the main monocyte chemoattractant CCL2 in rats or genetic deletion of its receptor CCR2 in mice decreased macrophage infiltration in response to injury and markedly inhibited liver fibrosis, implicating monocyte recruitment as an essential component in liver fibrogenesis." (PMID 28018292, 2016). "Although CCL2 is mostly produced by monocytes in the peripheral blood, the inflammatory CD14+CD16+ monocyte subset has been found to be the major source of CCL2 in HIV-infected individuals as well as in liver fibrosis." (PMID 25528160, 2014). "Our study indicates that the levels of sFasL and CCL-2 are reflective of the degree of liver fibrosis rather than the inflammatory features of NASH." (PMID 23405244, 2013). "Expression of the gene regulated on activation, T cell expressed, and secreted (RANTES; Ccl5), which is associated with severe liver fibrosis, was also significantly upregulated in HFHC-fed Dpp4–/– mice, whereas no changes in Mcp-1 (Ccl2) or Eotaxin (Ccl11) gene expression were noted." (PMID 36472923, 2023). "Therefore, we propose that during the progression of liver fibrosis (especially HBV related), there might be an “amplification loop” between aHSCs and macrophages, and CCL2/CCR2 axis has essential roles in this loop." (PMID 33614685, 2021). "CCL2 could recruit CCR2+Ly-6Chi monocytes to develop into Ly-6C+ macrophages in the damaged liver; then, these Ly-6C+ macrophages provoked hepatic stellate cells (HSCs) and promoted hepatic fibrosis in mice." (PMID 33623529, 2021). "CCL-2 is an important chemokine involved in the recruitment of monocytes/macrophages and T cells to areas of inflammation, with high prooncogenic action regulated in the liver, playing crucial roles in recruitment of monocytes and activation of HSC in the induction of hepatic fibrosis." (PMID 31780860, 2019). "Interestingly, despite the fact that serum levels of the candidate biomarkers CCL-2 and sFasL were not different between cohorts, an analysis by multiple linear regression showed that CCL-2, along with HDL levels, were independent predictors of advanced hepatic fibrosis (p<0.028)." (PMID 23405244, 2013).